KCNJ8 (potassium inwardly rectifying channel subfamily J member 8)
Diseases named in the same sentence as KCNJ8 in open-access papers:
KCNJ8 is named in the same sentence as 90 diseases in open-access papers, as found by Europe PMC text mining. Sharing a sentence is not in itself a finding about the gene and the disease. The quoted sentences say what the papers report.
Cantú syndrome (34 papers, 2016 to 2025). "Cantú syndrome (CS) is a rare genetic disorder caused by gain-of-function (GOF) mutations in the KCNJ8 (Kir6.1) or ABCC9 (SUR2) subunits of ATP-sensitive potassium (KATP) channels." (PMID 41020224, 2025). "Background/Objectives: Cantú syndrome is a rare autosomal dominant genetic disorder caused by gain-of-function variants in the ABCC9 or KCNJ8 genes." (PMID 40943777, 2025). "Gain-of-function (GOF) mutations in either Kir6.1 (encoded by KCNJ8) or SUR2 (encoded by ABCC9) are causally associated with Cantu syndrome (CS), characterized by coarse facial appearance, hypertrichosis, and multiple cardiovascular abnormalities." (PMID 41448431, 2025). "LMC function is impaired in Cantú syndrome, the only known example of primary lymphedema produced by a gene mutation (Kcnj8/Abbc9) in LMCs." (PMID 41279936, 2025). "The gain of function (GOF) mutations of the ABCC8 and KCNJ8 subunits is associated with Cantu syndrome, which is characterized by cardiovascular phenotypes in human and animals, and cases of pituitary adenoma in some families." (PMID 39200356, 2024). "In this study, we investigated changes in the vascular endothelium in mice in which Cantú syndrome–associated Kcnj8 or Abcc9 mutations were knocked in to the endogenous loci." (PMID 39088268, 2024). "Gain-of-function mutations in KCNJ8 or ABCC9 result in Cantu syndrome, a rare genetic disorder characterized by excessive hair growth, distinctive facial features, and an enlarged heart." (PMID 38302135, 2024). "For instance, a patient with Cantu syndrome (case 23) caused by a heterozygous variant in KCNJ8 (NM_004982.3: c.41T > G, p.Leu14Arg) was diagnosed through a further analysis of the NGS data." (PMID 34122524, 2021). "The V65M variant in the KCNJ8 gene was associated with Cantú syndrome, a rare genetic condition characterized by congenital hypertrichosis and cardiovascular abnormalities including an enlarged, hypercontractile heart." (PMID 33329049, 2020). "Activating mutations in the ABCC9 and, less commonly, KCNJ8 genes—representing the two subunits of the ATP-sensitive potassium channel—have been linked with Cantú syndrome." (PMID 29327300, 2018). "There is, however, one single case of a boy with Cantú syndrome due to a KCNJ8 gene mutation found with GH deficiency." (PMID 29327300, 2018). "Cantú syndrome is a multisystem disorder caused by gain-of-function (GOF) mutations in KCNJ8 and ABCC9, the genes encoding the pore-forming inward rectifier Kir6.1 and regulatory sulfonylurea receptor SUR2B subunits, respectively, of vascular ATP-sensitive K+ (KATP) channels." (PMID 39088268, 2024). "Furthermore, more than half of the patients with Cantu syndrome, a condition characterized by gain-of-function mutations in KCNJ8 or ABCC9, present with symptomatic PDA at birth." (PMID 39303216, 2024). "Recently, mice and humans affected by Cantu syndrome (CS), which is associated with the mutations of the KCNJ8 and ABCC9 genes encoding for the Kir6.1 and SUR2 subunits, showed dysfunction of contractility throughout the intestine and death in the mice after the weaning on solid food." (PMID 37446251, 2023). "Previous studies have demonstrated that Cantu syndrome–associated mutations in KCNJ8 resulted in cardiac hypertrophy, but the pathogenesis remains unclear." (PMID 36138345, 2022). "More rarely, Cantú syndrome can be caused by mutations in the KCNJ8 gene." (PMID 29327300, 2018). "Cantú syndrome (CS) is a rare autosomal dominant disorder caused by gain-of-function variants in the ABCC9 and KCNJ8 genes, which encode subunits of ATP-sensitive potassium (K_ATP) channels." (PMID 40943777, 2025). "Autosomal dominant GOF mutations in KCNJ8 and ABCC9, encoding Kir6.1 and SUR2, respectively, cause Cantú syndrome and associated cardiovascular abnormalities." (PMID 39088268, 2024).
Cantú syndrome (continued). "Pituitary macroadenoma has been observed in Cantu’ syndrome (C.S.), which is associated with the gain-of-function mutations of the ABCC9 and KCNJ8 genes." (PMID 37180726, 2023). "For example, Cantú syndrome patients, frequently affected by PDA, have monoallelic activating mutations in ABCC9 or KCNJ8, which form KATP channels." (PMID 34350653, 2022). "Dramatic cardiomegaly arising from gain-of-function (GoF) mutations in the ATP-sensitive potassium (KATP) channels genes, ABCC9 and KCNJ8, is a characteristic feature of Cantú syndrome (CS)." (PMID 32865539, 2020). "Cantù syndrome (CS) arises from mutations in ABCC9 and KCNJ8 genes that lead to gain of function (GOF) of ATP-sensitive potassium (KATP) channels containing SUR2A and Kir6.1 subunits, respectively, of KATP channels." (PMID 33329006, 2020). "Cantú syndrome (CS) was first described in 1982, and is caused by pathogenic variants in ABCC9 and KCNJ8 encoding regulatory and pore forming subunits of ATP‐sensitive potassium (KATP) channels, respectively." (PMID 32100467, 2020). "Three of these lines carry gain-of-function mutations in genes encoding the pore-forming (Kir6.1, KCNJ8) and regulatory (SUR2, ABCC9) subunits of an ATP-sensitive potassium channel (KATP) linked to Cantú syndrome (CS)." (PMID 30355756, 2018). "Mice and humans affected by Cantu syndrome (CS), which is associated with the mutations of the KCNJ8 and ABCC9 genes encoding the Kir6.1 and SUR2 subunits, showed dysfunction of contractility throughout the intestine and death in the mice after the weaning on solid food." (PMID 37446251, 2023). "Some links in the non-OMIM sources and supported by the older literature have been deemed not strong enough to deserve a separate entry in OMIM, e.g. the link between KCNJ8 and Cantú syndrome reported in DECIPHER or a link between PLXND1 and Moebius syndrome in Orphanet." (PMID 33836063, 2021). "Cantu syndrome (CS) is caused by gain-of-function (GOF) mutations in pore-forming (Kir6.1, KCNJ8) and accessory (SUR2, ABCC9) ATP-sensitive potassium (KATP) channel subunits, the most common mutations being SUR2[R1154Q] and SUR2[R1154W], carried by approximately 30% of patients." (PMID 33529173, 2021). "Cantú syndrome (CS) is caused by the gain of function mutations in the ABCC9 and KCNJ8 genes encoding, respectively, for the sulfonylureas receptor type 2 (SUR2) and the inwardly rectifier potassium channel 6.1 (Kir6.1) of the ATP-sensitive potassium (KATP) channels." (PMID 36980269, 2023). "The specific expression of KCNJ8 and ABCC9 in vascular mural cells, in particular brain PC, may suggest a role for these cells in the pathogenesis of Cantú Syndrome." (PMID 27725773, 2016).
cardiac hypertrophy (8 papers, 2014 to 2023). "Cardiac hypertrophy is also present in genome-edited “Cantú mice,” in which human disease-associated mutations were introduced into either the endogenous ABCC9 or KCNJ8 genes, despite no apparent alteration of KATP channel properties in the ventricular myocytes of KCNJ8-mutant (Kir6.1wt/VM) mice." (PMID 32865539, 2020). "As for mRNAs shown in the results of KEGG analysis of LINC00310, accumulated data have shown that KCNJ8 and SRF participate in the progression of pathologic cardiac hypertrophy." (PMID 36138345, 2022).
Hypertension (8 papers, 2019 to 2024). The presence of chronic increased pressure in the systemic arterial system. "Minoxidil had the most negative correlation coefficient (−0.3101) and is a hypertension medication that targets KCNJ8, KCNJ11, and ABCC9." (PMID 39713369, 2024).
diabetes (6 papers, 2018 to 2024). "SNPs in ATP-sensitive potassium channel (KATP) subunits KCNJ8 (Kir6.1) and ABCC9 (SUR2) might influence the presence of diabetes, and they seem to be involved in ischemic heart disease pathogenesis." (PMID 30344267, 2018).
atrial fibrillation (3 papers, 2018 to 2023). A disorder characterized by an electrocardiographic finding of a supraventricular arrhythmia characterized by the replacement of consistent P waves by rapid oscillations or fibrillatory waves that vary in size, shape and timing and are accompanied by an irregular ventricular response. "Moreover, a KCNJ8 mutation was also found to be associated with atrial fibrillation (AF), and KATP channel currents were found to be decreased during chronic human AF." (PMID 30596400, 2018).
Brugada syndrome (3 papers, 2021 to 2024). "One example, KcnJ8, which encodes an ATP-sensitive potassium channel (K-ATP), is widely expressed in different tissues and has been linked to cardiac disorders, specifically early repolarization syndrome (ERS) and Brugada Syndrome (BrS)." (PMID 38167534, 2024).
breast carcinoma (2 papers, 2013 to 2023). "We tested the role of the ABCC8/Sur1, ABCC9/Sur2A/B, KCNJ11/Kir6.2, and KCNJ8/Kir6.1 genes experimentally in a minoxidil-induced renal tumor in male rats and in the female canine breast cancer, a spontaneous animal model of disease, and in the pharmacovigilance and omics databases." (PMID 37180726, 2023). "The ABCC9 and KCNJ8 genes’ upregulation was associated with a reduced probability of survival in lung squamous cell carcinoma in males and the ABCC9 gene also in bladder and breast cancers in white female patients." (PMID 37180726, 2023). "Similarly, the ABCC9 and KCNJ8 genes’ upregulation was associated with a reduced probability of survival in lung squamous cell carcinoma in males, and the ABCC9 gene also in bladder and breast cancers in white female patients." (PMID 37180726, 2023).
lymphedema (2 papers, 2023). Excess fluid collection in tissues, causing swelling. "In this issue of Function, Davis and colleagues use mouse models of CS to investigate the underlying mechanism of primary lymphedema with GoF mutations in the KATP channel genes Kcnj8 and Abcc9." (PMID 37342412, 2023).
melanoma (2 papers, 2024 to 2025). A malignant, usually aggressive tumor composed of atypical, neoplastic melanocytes. "Other ARGs, including OLR1, KCNJ8, APP, POSTN, and STC1 showed significant yet heterogenous relationships with immune cells subsets, reinforcing the complexity of immune regulation in melanoma." (PMID 40943183, 2025).
pituitary adenoma (2 papers, 2023 to 2024). "Minoxidil treatment is a pharmacological animal model of C.S. This disorder is associated with G.O.F. mutations of the ABCC9 and KCNJ8 genes, and some cases of familial pituitary adenoma were found in C.S. families." (PMID 37180726, 2023).
viral infection (2 papers, 2024). "Datasets from the Immunological Genome Project (ImmGen) mouse database show that Kcnj8 is highly expressed in spleen CD27-/CD11b+ NK cell subsets and, upon viral infection, is strongly upregulated in cytotoxic CD8+ T cells." (PMID 39687626, 2024).
Arrhythmia (1 paper, 2021). Any cardiac rhythm other than the normal sinus rhythm. "Eight of these (50.0%) carried additional variants in other genes, including KCNJ8, SCN5A, SCN10A, ABCC9, and other genes related to inherited arrhythmias." (PMID 34222376, 2021).
cardiac arrest (1 paper, 2013). Cessation of breathing and/or cardiac function. "On the other hand, Kir6.1, encoded by KCNJ8, is upregulated in cardiomyocytes and has been reported to be involved in the pathogenesis of cardiac arrest in the early repolarization syndrome." (PMID 23690787, 2013).
glioma (1 paper, 2024). A benign or malignant brain and spinal cord tumor that arises from glial cells (astrocytes, oligodendrocytes, ependymal cells). "Conducting an extensive search using PubMed on glioma/brain-cancer-related articles of ABCC8, ABCC9, KCNJ11, KCNJ8, AQP4, and KCNMA1 genes has yielded interesting results." (PMID 39200356, 2024). "In the present work, we showed that the AQP4 aggregation into the pathogenic AQP4-tetramer and AQP4-OAPs differently affected the expression profile of KCNMA1, KCNJ11, ABCC8, and ABCC9 genes but not of the KCNJ8 gene in the U87 glioma cell, evaluated by the RTPCR gene expression." (PMID 39200356, 2024).
lung carcinoma (1 paper, 2025). "M5 expressed pericyte-associated genes (RGS5, PDGFRB, NES, THY1, KCNJ8) and showed strong similarity to curated pericyte signatures, including pan-cancer C8_RGS5 pericytes, healthy human prostate pericytes and pericytes from lung cancer." (PMID 41378308, 2025).
neuroblastoma (1 paper, 2011). Neuroblastoma (NB) is the most common solid, extracranial childhood tumor. "The genes exhibiting methylation values above normal samples include the oncogene PHOX2B, the neuroblastoma associated gene ALX3, the commonly methylated PCDHα gene cluster, POU4F2, REXO1L1, BAPX1, and the potassium-channel KCNJ8." (PMID 22174824, 2011).
short QT syndrome (1 paper, 2023). A genetic disease of the electrical system of the heart that consists of a constellation of signs and symptoms, consisting of a short QT interval on an EKG (< 300 ms) that does not significantly change with heart rate, tall and peaked T waves, and a structurally normal heart. "KCNJ8 and ABCC9: Mutations in both KCNJ8 (Kir6.1) and ABCC9 (SUR2A) genes can result in a gain-of-function effect in the IK-ATP channel, leading to abnormal action potential characteristics associated with BrS or short QT syndrome phenotypes." (PMID 37443825, 2023).
tumor (9 papers, 2021 to 2025). "In NSCLC, the overexpression of SUR1 (KCNJ8 or Kir6.1) promotes cell proliferation, and silencing KCNJ8 or glibenclamide treatment decreases cell and tumor growth, as well as increasing expression of the tumor suppressor Krüppel-like factor 4 (KLF4)." (PMID 37408210, 2023). "In this array, KCNJ8 showed a higher expression in CAFs (FAP+) compared to tumor epithelial (EpCAM+) cells." (PMID 33802791, 2021). "Therefore, Kcnj8 deficiency does not seem to affect overall NK-cell cytotoxicity under these specific conditions or tumor cells tested." (PMID 39687626, 2024). "In particular, the GSE34053 dataset analyzed cancer-associated fibroblasts (CAF, tumor stromal cells) and CD133+ cells (tumor epithelial cells); while CD133+ cells expressed higher levels of KCNAB2 and KCNMB4, CAF cells (stroma) overexpressed SCN9A and KCNJ8 subunit channels." (PMID 33802791, 2021). "Clusters 4 and 5 mainly derived from tumor tissues and were designated as pericytes due to their high expression of RGS5 and KCNJ8." (PMID 37853464, 2023). "Pericyte-1 was enriched in the tumor fraction and characterized by higher expression of genes related to a pro-inflammatory capillary phenotype (RGS5, KCNJ8, AXL, ABCC9, PDGFRB, and THY1)." (PMID 36180422, 2022). "While the comparison of expression data between tumor and normal samples showed that 8 out of 36 ARGs were significantly differentially expressed, including CCND2, CXCL6, KCNJ8, LPL, SERPINA5, SLCO2A1, VTN, and APOH." (PMID 35836112, 2022). "Kcnj8 does not participate in NK cell degranulation in response to tumor cells in vitro or rejection of tumor cells in vivo, or IFN-γ release." (PMID 39687626, 2024). "Similarly, LRPAP1 and KCNJ8 showed negative correlations with CD8+ T cells and positive correlations with macrophages and certain memory B cell subsets, suggesting that these genes may shift immune cell composition in ways that impact tumor immunity." (PMID 40943183, 2025).
cancer (6 papers, 2020 to 2025). A tumor composed of atypical neoplastic, often pleomorphic cells that invade other tissues. "Our data also support the safe use of zoledronic acid as a KATP channel blocker in the treatment of macroadenoma in C.S. associated with G.O.F. mutations of the ABCC9 and KCNJ8 genes or in cancers in which these subunits were associated with poor prognosis." (PMID 37180726, 2023). "Also, pharmacovigilance data were analyzed to assess the correlation of ABBC8, ABCC9, KCNJ11, and KCNJ8 genes with cancer reactions induced by drugs targeting the different KATP channel subunits." (PMID 37180726, 2023). "The minoxidil-induced overactivation of Kir6.1/2-Sur2A/B subunits in rats provoked a cancer reaction similar to what was observed in some cases of C.S. Omics data reporting the upregulation of the ABCC9, KCNJ11, and KCNJ8 genes in cancers support these conclusions." (PMID 37180726, 2023). "This study revealed that the KCNJ8, KCNJ11, ABCC8, ABCC9 genes are downregulated in cancer of the female reproductive tract when compared with the correspondent normal tissues." (PMID 32457608, 2020). "KCNJ11, KCNJ8, and ABCC9 genes are upregulated in cancers but ABCC8 is downregulated." (PMID 37180726, 2023).
infection (3 papers, 2009 to 2025). The state of being infected such as from the introduction of a foreign agent such as serum, vaccine, antigenic substance or organism. "A striking exception is that Kcnj8 and Abcc9 expression is strongly upregulated in liver macrophages after 8-48 h infection with C. Albicans." (PMID 39669557, 2024). "Because Kcnj8 and Abcc9 expression matches those cells that have developed or innate functions to rapidly respond to infections or immune stressors, KATP channels may have a role in responses to these stressors." (PMID 39669557, 2024). "We identified ten NK subgroup-specific marker molecules (Kcnj8, Cmah, Ccnd2, Cx3cr1, Thy1, Tnfrsf9, Zbtb20, Gng11, CD226, Egr3) from C0 to C9 and assessed their expression changes during infection using RT-qPCR." (PMID 40244063, 2025). "Functions of Kcnj8 and Abcc9 need to be explored in NKT cells, NK cells, and macrophages and CD8+ T cells following infection." (PMID 39669557, 2024).
KCNJ8 also shares sentences with these, for which no sentence is quoted: migraine (6 papers); endotoxemia (3); heart failure (3); ischemia (3); metabolic disease (3); preeclampsia (3); cardiomyopathy (2); depression (2); early repolarization syndrome (2); endothelial dysfunction (2); Hyperglycemia (2); Hypoglycemia (2); Insulin resistance (2); migraine headaches (2); pulmonary hypertension (2); Sepsis (2); type 2 diabetic (2); Alzheimer disease (1); atrioventricular block (1); cardiovascular disease (1); cerebral infarcts (1); Cerebral ischemia (1); cervical cancer (1); Char syndrome (1); chronic heart failure (1); colitis (1); cryptorchidism (1); diabetic cardiomyopathy (1); DiGeorge syndrome (1); esophageal squamous cell carcinoma (1).
A further 40 diseases each share a sentence with KCNJ8 in 1 paper.